KRAS (KRas proto-oncogene, GTPase)
Diseases named in the same sentence as KRAS in open-access papers (continued):
Sharing a sentence is not in itself a finding about the gene and the disease.
cancer (continued). "HRAS-mutated cancers are still potential therapeutic targets of FTIs such as tipifarnib despite the negative results of FTIs against NRAS- or KRAS-mutated cancers." (PMID 40243851, 2025). "Furthermore, it has been demonstrated that the metallopeptide αH-His2 [Pd] binds to KRAS, which is a critical step in inhibiting the MAPK kinase cascade and ultimately leading to the suppression of cancer cell proliferation." (PMID 40003893, 2025). "Moreover, high FUT1 expression had a significant impact on estrogen response, KRAS signaling, and TNF-α signaling via NF-κB pathways in most cancer types." (PMID 40084262, 2025). "A significant difference in dependency based on copy number status was also observed in the non-mutated cell lines for KRAS, but not for BRAF, suggesting that for KRAS also increasing the non-mutated copy number is beneficial for the cancer cells." (PMID 40694850, 2025). "Unlike KRAS, NRAS, and HRAS, MRAS mutations are rare in human cancers due to their lower affinity for RAF proteins and reduced ability to activate the ERK pathway." (PMID 41170373, 2025). "RNA-seq analysis were performed in cancer cells bearing different status of ANO1 and KRAS." (PMID 40396170, 2025). "Genetic alterations in key components of these pathways, such as EGFR, BRAF, KRAS, PIK3CA, and PTEN, have been well-documented in NSCLC, and our study suggests that CKS1B may play a role in modulating these alterations to drive cancer progression." (PMID 40165937, 2025). "In subgroup analysis, Patients with KRAS or NRAS mutant tumors should not be treated with cetuximab alone or in combination with other anti-cancer drugs, as they have little chance of benefit and hence the exposure to toxicity and expense are not justified." (PMID 41262255, 2025). "Our previous study found that KRAS and BRAF mutations in ctDNA are not predictive of cancer relapse, suggesting that the use of these mutations in ctDNA alone is insufficient for recurrence prediction." (PMID 40698441, 2025). "Early preclinical studies have demonstrated that KRAS-targeting PROTACs, including degraders specific for KRAS G12D and KRAS G12V mutants, effectively reduce KRAS protein levels and suppress downstream MAPK signaling in various cancer cell lines and xenograft models." (PMID 40361439, 2025). "Notably, mutant KRAS is the most frequent driver of several cancers: about 27% of all human cancers, 45% of colorectal, and 90% of pancreatic cancers." (PMID 40130618, 2025). "This dysregulation is most commonly caused by somatic, gain-of-function point mutations in key upstream nodes, particularly the RAS (e.g., KRAS, NRAS) and RAF (e.g., BRAF) families of proto-oncogenes, as comprehensively documented in large-scale cancer genome analyses." (PMID 41361128, 2025). "Evidence exists in other cancers demonstrating EGFR activity is needed for full activation of MEK and ERK downstream of mutant KRAS and this may be the first example of that in NSCLC, reinforcing a need to target BACE1 in this setting." (PMID 40601773, 2025). "Further, the exploration of valine–niclosamide’s activity against NF-kB, STAT3, KRAS, and other oncogenic pathways that demonstrate rebound activity following AR-KO is necessary in HCC, PCa, and other cancers to demonstrate the maintenance of key types of activity across cancer types." (PMID 40805231, 2025). "Like KRAS/LKB1 co-mutation, KRAS/KEAP1 co-mutation is a negative prognostic factor in KRAS mutant cancer." (PMID 40611261, 2025). "Similarly, we also identified differences in isoform usage between KRAS-201 (KRAS4a) and KRAS-202 (KRAS4b), as well as between USO1-201 and USO1-204, which have been reported as functionally relevant in cancer." (PMID 40702779, 2025).
cancer (continued). "However, upon chronic inflammation and injury or sustained oncogenic activation of the small GTPase KRas, ADM can become persistent and result in the formation of pancreatic neoplasia and cancer." (PMID 40490362, 2025). "The aggressive nature of lapatinib-resistant cells is evident compared to their cancer counterpart, as our analysis shows significant anchorage-independent growth, which correlates with hyperactivation of the MAPK and KRAS pathways, leading to an enhanced transformational potential." (PMID 40946111, 2025). "In pancreatic cancer models, linsitinib, which inhibits IGF1 or IGF‐1 receptor along with AKT, favors the elimination of dormant cancer cells not expressing mutant KRAS or c‐MYC." (PMID 41020040, 2025). "On the basis of the first in silico study, the Ph-Asc and the repurposed anti-malarial agent CQ combined treatment was tested on different KRAS mutant and non-mutant cancer cell lines." (PMID 40076255, 2025). "Enhancing knowledge about miRNA-regulated pathways, like KRAS, AKT, JAK/STAT/WNT/β-catenin, and TGF-β, could lead to strategies for treating cancer." (PMID 40699746, 2025). "Unlike canonical oncogenes, like BRAF or KRAS, FOXM1 is not commonly mutated nor amplified in cancer, warranting its exclusion from common “cancer gene lists” such as the Sanger Institute’s COSMIC Cancer Gene Census." (PMID 39858603, 2025). "According to the in silico model, the positive feedback loops of both KRAS and mTOR pathways may have key roles in determining the GLUT1 expression and autophagy induction upon cancer development." (PMID 40076255, 2025). "Therefore, the direct inhibition of KRAS and the indirect inhibition of different stages of the MAPK pathway can provide anti-cancer efficacy." (PMID 40731832, 2025). "In contrast, KRAS and growth factor receptor mutations like FGFR and EGFR are generally mutually exclusive in cancer, resulting in a lack of sensitivity to the latter in the KRAS hotspot population." (PMID 41168869, 2025). "We propose that the STAT3 transcriptional program operating in cancer cells enforces their malignant identity, rather than providing classical features of transformation, and shapes cancer persistence following KRAS inactivation." (PMID 40859018, 2025). "In contrast, another research showed that in multiple kinds of cancer, LKB1 or KEAP1 co-mutation tended to be accompanied by KRASG12C rather than other types of KRAS mutations." (PMID 40611261, 2025). "Mutant KRAS allows cancer cells to survive and proliferate under glucose-deprived conditions, unlike normal cells or KRAS wild-type cancer cells." (PMID 40429703, 2025). "Upon binding to the mutant, RMC-9805 forms a stable complex with KRAS G12D and cyclophilin A, leading to suppression of RAS pathway activity, inhibition of cancer cell proliferation, and apoptosis induction in vitro and in most preclinical PDAC and NSCLC cancer models when used alone." (PMID 40597785, 2025). "Despite its recognized importance in cancer malignancy, KRAS is considered non-druggable and has never been studied in the field of ATC." (PMID 40141222, 2025).
cancer (continued). "Notably, Patient 63 had a KRAS G12V, SMAD4, GNAS, and KMT2C mutant-positive PDAC with liver metastases while Patient 64′s cancer was BRAF V600E-positive, and they had also undergone treatment with experimental BRAF and MEK inhibitors." (PMID 39941724, 2025). "We then asked if this pattern (a statistically significant alteration of the ‘KRAS Signaling Down’ pathway between the PSG+ and PSG− groups in female LUAD patients grouped by the signature of PSG3, PSG7, and PSG8) is present in other TCGA cancer datasets." (PMID 40257008, 2025). "BRAF MT tumors were significantly more prevalent in the MSI-H population, constituting 62.8% of this subgroup (p<0.001), while All-WT, KRAS MT, and NRAS MT cancer specimens were less frequent, accounting for 21.1%, 15.4%, and 0.7%, respectively (p<0.001 for each)." (PMID 39628993, 2024). "Herein, we describe the biological and preclinical characterization of IAG933 and its close analogs, their monotherapy activity in specific Hippo-dependent cancers and in combination with receptor tyrosine kinases (RTKs), KRAS, BRAF, MEK or ERK inhibitors in a broad range of other cancer models." (PMID 38565920, 2024). "Thus, a pan-KRAS inhibitor would be expected to have broader use for CRC and other RAS driven cancers given its additional potential to circumvent resistance from unchecked activity of WT RAS isozymes." (PMID 38978742, 2024). "Mechanistically, mutant KRAS upregulates SG formation by stimulating the production of prostaglandin 15-d-PGJ2 which enables paracrine control of SG, eventually resulting in resistance of cancer cells to stress stimuli." (PMID 39390257, 2024). "Studies have shown that tumors with aberrant activation of the RAS/RAF/MEK/ERK pathway, such as KRAS-mutant cancers, do not respond to PI3K pathway inhibitors." (PMID 39070139, 2024). "Also, the cancer was already metastatic (stage IV) at diagnosis somewhat more often in patients with KRAS mutation than in other patient groups (KRAS G12C n = 12, 57%; other KRAS n = 31, 61%; other driver mutation n = 22, 43%; no driver mutations n = 61, 44%) indicating more aggressive disease." (PMID 38785486, 2024). "Somatic genetic variations in APC, KRAS, BRAF, and PIK3CA genes are the most frequent in CRC, leading to the activation of key WNT–β-catenin and MAPK signal transduction pathways, which subsequently promote cell proliferation and cancer progression." (PMID 37863651, 2024). "In the context of aggressive diseases, KRAS is overexpressed in about 30% of all human cancers including 95% of pancreatic and 45% of colorectal and non-small-cell lung cancer (NSCLC)." (PMID 39457457, 2024). "Though we did not notice positive correlation between KRAS and MTOR in PAAD, CRAD, and LUAD, in studying cBioPortal, we observed the existence of a co-mutation of these two factors in cancer." (PMID 39056802, 2024). "and it does not interact with the H95 residue on KRAS, leading to potential for other Ras G12C-mutant cancers." (PMID 39372214, 2024).
cancer (continued). "By contrast, Deltaflexin3 displayed the overallhighest selectivityfor PDE6D-dependent and KRAS mutant,as compared to HRAS mutant cancer cell lines, consistent with its K-RasG12V selectivity detectedby BRET and its off-target activity being lowest among the investigated compounds." (PMID 38758695, 2024). "This analysis highlighted the BRCA1–HDAC2 and KRAS–HMGCR pairs, offering valuable insights into potential vulnerabilities in cancer cells that could be exploited by Simvastatin and Lovastatin." (PMID 39217242, 2024). "Additionally, BAY 11-7082 inhibitor treatment leads to downregulation of several specific oncogenic signaling pathways in NRAS, KRAS, and HRAS mutant cancer cells." (PMID 38982514, 2024). "Our analyses do not support that SG are formed during tumorigenesis of KRAS-driven cancers, at least that their presence is not universal, leading us to propose that caution is required before considering SG as therapeutic targets." (PMID 39390257, 2024). "Most recently, the pan-KRAS inhibitors and the pan-RAS inhibitor RMC-7977 have been tested in preclinical models, demonstrating the potential to treat various RAS-driven cancers, including PDAC." (PMID 39518005, 2024). "Among all combination strategies to enhance the antitumor activity of KRAS G12C inhibitors, the inhibition of SHP2, which connects RTKs to the RAS signaling pathway and is particularly vulnerable in cancer cells with genetic alteration in KRAS, has attracted considerable attention." (PMID 39704172, 2024). "As expected, KRAS-mutant cancer cell lines were more sensitive to a commercially available MEK inhibitor, trametinib, than were KRAS wild-type cancer cell lines based on screening data from The Genomics of Drug Sensitivity in Cancer Project (GDSC)." (PMID 38992694, 2024). "In view of the promising prospects, a bibliometric analysis of the research of KRAS-mutant cancer should never have remained vacant." (PMID 38706597, 2024). "In patients with EGFR mutations, and without either KRAS or EGFR mutations, cancer stage was only predictive of OS but not RFS." (PMID 39385301, 2024). "This phenomenon has also been observed in KRAS-driven pancreatic ductal adenocarcinoma (PDAC) cancer models but not in other cancer models in mice." (PMID 39795113, 2024). "Indeed, KRAS mutant CRC harbors a boosted glucose metabolism as well as deregulation of glutamine, amino-acid, and fatty acid metabolism that support cancer cell proliferation." (PMID 39456549, 2024). "Clinical trials involving inhibitors against RAF and MEK have not received approval for treating KRAS-mutant cancers." (PMID 38668053, 2024).
cancer (continued). "Studying EMT in cancer cell lines that express known oncogenes (e.g., PTEN, KRAS) may confound the contribution of SETD2 to the process of tumorigenesis." (PMID 37418588, 2024). "KRAS-mutant mCRC urgently needs more (targeted) therapeutic options; patients with these cancers do not respond to the otherwise clinically beneficial strategies blocking the pathway KRAS is involved in signalling." (PMID 39516561, 2024). "Finally, several cancer type-specific changes in epithelial-to-mesenchymal transition (EMT) and key intracellular signaling pathways such as MYC, MTORC1, or KRAS, occurred in female and male cases with midrange TI values." (PMID 38622740, 2024). "Targeting the CDK9/ERK/MYC network in cancer cells, as well as their crosstalk with the TME via the complement system may yield improved responses in KRAS‐mutant patients." (PMID 39254172, 2024). "KRAS G12D directly drives the expression of the glycoprotein, intracellular adhesion molecule 1 (ICAM1), which is abnormally overexpressed in a variety of cancers including PDACs." (PMID 39409965, 2024). "Interestingly, the distributions of several known cancer driver genes exhibit significant differences between cancer and normal tissues, such as FAT4, KMT2C, KMT2D, KRAS, PIK3CA, and PTEN." (PMID 39541191, 2024). "Both KRAS and MYC have been categorized as undruggable cancer targets." (PMID 39457457, 2024). "KRAS cycles through ON and OFF states, controlling the downstream effectors, including the MAPK, PI3K, and RALGDS pathways and many others, promoting the growth and survival of cancer cells." (PMID 39594840, 2024). "We find that oncogenic NRAS, KRAS, and HRAS activate the expression of IkappaBalpha (IκBα) and BAY 11-7082, an inhibitor of IκBα kinase, attenuates the growth of NRAS, KRAS, and HRAS mutant cancer cells in cell culture and in vivo mouse model." (PMID 38982514, 2024). "Although KRASG12C inhibitors have recently been approved, effective precision therapies have not yet been established for all KRAS-mutant cancers." (PMID 38992694, 2024). "These new findings explain why dual inhibition of SUMOylation and MEK induced dramatic antitumor responses in MYC-expressing KRAS-mutant cancer cells in vitro and in vivo without immune reactions." (PMID 38992694, 2024). "The most striking example is the KRAS G12C variant that was not actionable until the approval of specific KRAS G12C inhibitors, which made it a potential pan-cancer biomarker." (PMID 39443383, 2024). "Except for subsequent line treatment for KRAS G12C-mutated NSCLC, none of KRAS G12C inhibitors has been approved by the FDA, though previous clinical trials included different types of cancer." (PMID 38756650, 2024).